FBN1 (fibrillin 1)
Diseases named in the same sentence as FBN1 in open-access papers (continued):
Sharing a sentence is not in itself a finding about the gene and the disease.
glaucoma (15 papers, 2008 to 2025). Increased pressure in the eyeball due to obstruction of the outflow of aqueous humor. "An intrinsic defect in the outflow pathway due to FBN1 mutations would be consistent with several long-standing observations in glaucoma research." (PMID 23444230, 2013). "Similarly, patients with MFS and Weill–Marchesani type 2 syndrome with mutations in FBN1 often develop elevated IOP as a result of glaucoma." (PMID 35285860, 2022). "In humans, mutations in FBN1 can result in glaucoma and pressure-induced buphthalmia." (PMID 30642872, 2019). "Our findings suggest that mutations in FBN1 and other genes involved in microfibril structure and function may be found in patients with pigmentary glaucoma and possibly other forms of glaucoma." (PMID 23444230, 2013). "Hence characterizing Tsk mice may help us better understand not only potential contributions of fibrillin-1 mutation to POAG pathogenesis but also putatively related (but as yet unidentified) disorders contributing to glaucoma." (PMID 38347040, 2024). "To further understand the possible mechanisms of glaucoma in this patient, we investigated expression in the aqueous humor outflow pathway of fibrillin-1 and elastic fibers, which are composed of elastin cores surrounded by fibrillin-1 microfibrils." (PMID 23444230, 2013). "This suggests that acupuncture may target specific genes involved in the treatment of glaucoma, such as MT3 (associated with ocular neovascularization) and FBN1 (related to macular degeneration)." (PMID 39378079, 2024). "In addition to sharing a phenotype, Tsk mice and human POAG subjects had common TGFβ and fibrillin-1 features in AH and also blood that are pertinent to understanding glaucoma pathogenesis." (PMID 38347040, 2024). "This hints that the mutation of FBN1 leads to hyperactivity of TGF-β and could thereby favor the onset of glaucoma." (PMID 34299278, 2021). "Lysyl oxidase-like 1, which is linked to Pseudoexfoliation (PEX) glaucoma, and which is heavily bound to the PEX material of PEX patients was very downregulated in Q368X, while other two PEX relevant components, FBN1 and Fibulin 5 (FBLN5), were slightly altered in all four mutants." (PMID 22615763, 2012). "Interestingly, samples from patients with XFS who had not (yet) developed glaucoma had noticeably less FBN1, LOXL1, and LEFTY2 than samples from patients with XFG." (PMID 34964803, 2021).
Acromicric dysplasia (14 papers, 2012 to 2026). A rare bone dysplasia characterized by short stature, short hands and feet, mild facial dysmorphism, and characteristic X-ray abnormalities of the hands. "Monoallelic disease-causing variants were identified in FBN1 (acromicric dysplasia, n = 3) and GNAS (Albright hereditary osteodystrophy (AHO), n = 1)." (PMID 42151490, 2026). "By performing skin biopsy, X‐ray imaging, electrocardiography, as well as whole‐genome sequencing and Sanger sequencing, we diagnosed an 8‐year‐old Chinese boy as acromicric dysplasia with severe skin stiffness caused by a heterogeneous mutation in the FBN1." (PMID 32406602, 2020). "A 24-bp in-frame deletion in domain TB5 linked to Weill–Marchesani syndrome and missense mutants linked to the geleophysic and acromicric dysplasias have been reported to alter the interactions of this region of fibrillin-1 with heparan sulphate." (PMID 25979247, 2015).
breast carcinoma (13 papers, 2016 to 2025). "COL3A1, COL11A1, and FBN1 are associated with maintaining a cancer stem-like phenotype in various cancers and therefore may be of interest in breast cancer." (PMID 35755802, 2022). "The effect of fibrillin-1 expression in the TME of breast cancer on prognosis is less understood." (PMID 39273393, 2024). "Caveolin-1, Desmin, microfibril associated glycoprotein 4, fibrillin 1 and collagenα-1 have been identified as potential biomarkers that can discriminate metastatic from non-metastatic sentinel lymph nodes in early breast cancer." (PMID 35599267, 2022). "According to the xiantao database, COL1A2, COL3A1, FGA, LUM, APOA1, APOH, and COL5A2 were more highly expressed in breast cancer than in normal tissues (p < 0.05), while the opposite pattern was seen for ALB and FBN1 (p < 0.05)." (PMID 37079213, 2023). "While collagen type I is well described as having a role in cancer cell proliferation, drug resistance, and motility, the matrix proteins such as COL3A1, COL11A1, FBN1, and MFAP2 are less explored in breast cancer." (PMID 35755802, 2022). "Variants in BICD2 (six cases), FBN1 (four cases), CSGALNACT1 (one case), and ZNF841 (one case) were observed in at least one UKBiobank breast cancer case, but not in any controls." (PMID 38136396, 2023). "Interestingly, recent studies suggest both a role for FBN1 and MYOD1 in breast cancer." (PMID 32850701, 2020).
dilatation (13 papers, 2013 to 2024). "The Ghent criteria comprise aortic dilatation, the presence of a mutation in the fibrillin-1 gene according to genetic tests, and the presence/absence of a family history of the disease." (PMID 27249938, 2016). "Patients with predicted PTC variants of FBN1 (leading to haploinsufficiency, quantitative defect) have more severe aortic dilatation and systemic manifestations than patients with predicted in-frame pathogenic variants (leading to a dominant negative effect, qualitative defect)." (PMID 38685042, 2024). "Furthermore, patterns of microstructural remodeling are comparable in all 12-week-old mice carrying the Fbn1 variant and mostly depend on the severity of aneurysmal disease." (PMID 38545339, 2024). "Progressive aortic dilatation was observed when both fibrillin-1 and IL-6 were deficient." (PMID 30883599, 2019). "Moreover, our group next identified for the first time pathogenetic FBN1 gene (fibrillin 1, 15q21.1, OMIM*134797) mutations in patients with BAV and aortic dilation/aneurysm in whom MFS and other more severe type 1 fibrillinopathies were clinically excluded." (PMID 28883797, 2017). "One small study investigated the genotype in relation to left ventricular (LV) function and noticed that LV dilatation in MFS patients is more often seen in patients with a non‐missense FBN1 pathogenic variant and in those patients without an FBN1 pathogenic variant." (PMID 29717556, 2018).
acromelic dysplasia (11 papers, 2015 to 2024). "Disorganization of the microfibrillar network and enhanced TGF-β signaling caused by FBN1 mutations can trigger either MFS or acromelic dysplasia." (PMID 39077065, 2024). "The combination of the cases we identified and previous case reports corresponded to 7 FBN1 variants that contributed to different phenotypes of acromelic dysplasia." (PMID 39077065, 2024). "A subset of FBN1 genetic mutations can cause acromelic dysplasias, a group of musculoskeletal disorders that share extremely short stature and stiff joint phenotypes." (PMID 38844137, 2024). "Targeted next-generation sequencing will make it possible to study the spectrum of FBN1 gene mutations efficiently and comprehensively, providing reference points for early screening and genetic counseling of acromelic dysplasia." (PMID 39077065, 2024). "In addition, a total of 8 reports about 15 individuals with acromelic dysplasia caused by FBN1 gene mutation treated with rhGH were retrieved." (PMID 39077065, 2024). "Summary of identical mutations in FBN1 related to different phenotypes of acromelic dysplasia." (PMID 39077065, 2024). "In addition, the clinical and genetic characteristics of different phenotypes of acromelic dysplasia due to identical FBN1 gene mutations and the efficacy of recombinant human growth hormone (rhGH) therapy in acromelic dysplasia are summarized." (PMID 39077065, 2024). "It has been proposed that the three-dimensional structure of fibrillin molecules (product of FBN1) within a microfibril may create a microenvironment consisting of domains that cause acromelic dysplasia." (PMID 37239376, 2023). "This review focuses on acromelic dysplasias associated with FBN1 and ADAMTS(-L) mutations." (PMID 34912367, 2021). "In addition to SSS, several mutations affecting fibrillin-1 have been linked to another series of disorders, known collectively as the acromelic dysplasias." (PMID 25979247, 2015). "Interestingly, also SEMA3A mutations may cause short stature, as can be observed in FBN1 mutation patients with acromelic dysplasias." (PMID 34895303, 2021). "Identical FBN1 genotypes can result in different phenotypes of acromelic dysplasia not only in different countries, but also within a family (such as AD and GD2)." (PMID 39077065, 2024). "Summary of rhGH therapy efficacy in FBN1-related acromelic dysplasia: present study and other reported cases." (PMID 39077065, 2024). "Taking “FBN1” AND “acromelic dysplasia” in English or Chinese as the keywords, literature was searched at PubMed, CNKI, and Wanfang up to April 2024." (PMID 39077065, 2024). "Here, we report two different acromelic dysplasia phenotypes (AD and GD2) in three members from a Chinese family associated with a missense mutation in exon 42 of the FBN1 gene c.5179C>T (p.Arg1727Trp)." (PMID 39077065, 2024). "We show that MFS-associated substitutions affecting domains TB4 and TB5 lead to a loss of fibrillin-1 from the cell culture medium whereas mutants associated with SSS and the acromelic dysplasias are secreted and detected in the extracellular media." (PMID 25979247, 2015). "Therefore, the clinical presentation of FBN1-related acromelic dysplasia is heterogeneous and variable, posing challenges for accurate diagnosis and clinical management." (PMID 39077065, 2024). "This suggests that, as in the case of the SSS mutants, the acromelic dysplasia mutants may be acting at the level of cell–matrix interactions rather than disrupting microfibril assembly and that heparan sulphate interactions involving this region of fibrillin-1 are not critical for assembly." (PMID 25979247, 2015).
cardiomyopathy (11 papers, 2013 to 2025). A disease of the heart muscle or myocardium proper. "Cardiomyopathy in fibrillin 1-deficient mice was demonstrated to result from a primary cardiac impairment that appeared to be caused by ECM-induced abnormal cardiomyocyte mechano-signaling." (PMID 40274989, 2025). "The authors identified specific genetic variants in the FBN1 gene associated with an increased risk of developing cardiomyopathy." (PMID 39900832, 2025). "These advances allow to decipher the effects of different pathogenic variants in FBN1 and other extracellular matrix variants that cause cardiomyopathy and uncover the disease mechanisms." (PMID 39830211, 2024). "Various tests were conducted on lab-bred mice regarding the role of FBN1 gene mutation on MFS-related cardiomyopathy to gain a greater insight into the pathophysiology of MFS." (PMID 36340521, 2022). "While FBN1 appears causative for MFS cardiomyopathy, these studies also warrant the necessity for a better understanding of the underlying mechanisms." (PMID 33028885, 2020). "Arrhythmia in the case of MFS is less likely to be seen in comparison to aortic root abnormality and cardiomyopathy, although it has been shown that people with FBN1 gene mutation have a higher prevalence of ventricular arrhythmia by around 48% in comparison to normal people." (PMID 36340521, 2022). "However, there is still debate about whether a form of primary cardiomyopathy related to the FBN1 mutation exists among MFS patients." (PMID 25901601, 2015). "FBN1 appears to be an effector of MFS cardiomyopathy, however these studies also warrant the necessity for a better understanding of the mechanisms responsible." (PMID 33028885, 2020). "Mouse data suggests that fibrillin-1 is widely expressed in the heart and aorta, and that MFS mice are particularly sensitive to increased arterial load, which leads to a pressure induced cardiomyopathy that can be prevented by Losartan." (PMID 35547588, 2022).
osteosarcoma (11 papers, 2016 to 2024). A usually aggressive malignant bone-forming mesenchymal neoplasm, predominantly affecting adolescents and young adults. "Silencing lncRNA-PGM5-AS1 increases miR-140-5p expression, which in turn reduces FBN1 levels, thereby attenuating in vitro osteosarcoma epithelial-mesenchymal transition (EMT), invasion and migration, and in vivo tumorigenesis." (PMID 38269088, 2023). "Reference 1 Liu W, Liu P, Gao H, Wang X, Yan M. Long non-coding RNA PGM5-AS1 promotes epithelial-mesenchymal transition, invasion and metastasis of osteosarcoma cells by impairing miR-140-5p-mediated FBN1 inhibition." (PMID 37471281, 2023). "In conclusion, this study suggested that the miRNAs including miR-22-3p, miR-154-5p, miR-34a-5p, miR-485-3p, miR-93-5p, and miR-9-5p and the genes including LEF1, RUNX2, CSF1R, CDKN1A, and FBN1 act as key factors in the progression of osteosarcoma." (PMID 35340229, 2022). "In summary, this study suggests the miRNAs including miR-22-3p, miR-154-5p, miR-34a-5p, miR-485-3p, miR-93-5p, and miR-9-5p and the genes including LEF1, RUNX2, CSF1R, CDKN1A, and FBN1 are the key factors in the progression of osteosarcoma." (PMID 35340229, 2022). "For example, lncRNA PGM5-AS1 directly bound with miR-140 in osteosarcoma cells to modulate downstream FBN1 pathway, thereby affecting invasion, migration and tumorigenesis of osteosarcoma." (PMID 34496800, 2021). "In contrast, PGM5-AS1 can weaken the inhibitory effect of fibrillin-1 which mediated by miR-140-5P, and promote epithelial-mesenchymal transition, invasion and metastasis of osteosarcoma cells." (PMID 34249715, 2021). "Reduced FBN1 is related with the high invasiveness and metastasis of osteosarcoma, and increased FBN1 could also inhibit the epithelial-mesenchymal transition of osteosarcoma cells." (PMID 35340229, 2022). "Thus, this study suggests that the hub nodes LEF1, RUNX2, CSF1R, VAV3, FZD3, CDKN1A, and FBN1 are key factors in the progression of osteosarcoma." (PMID 35340229, 2022). "Interfering with the expression of FBN1 in osteosarcoma cells inhibits cell migration and invasion." (PMID 34692659, 2021). "A high level of FBN1 may also promote osteosarcoma invasion, migration, and progression." (PMID 38269088, 2023).
emphysema (10 papers, 2006 to 2025). "It has been described that fibrillin-1-deficient (Fbn1mgΔ/mgΔ) mice display impaired distal alveolar septation in the early postnatal period and develop emphysema at an older age." (PMID 27585882, 2016). "Heterozygotes for the mutant Fbn1 allele mgΔloxPneo, carrying the same internal deletion of exons 19–24 as the mgΔ mouse model, present defective microfibrillar deposition, emphysema, deterioration of aortic wall and kyphosis." (PMID 21152435, 2010). "In patients with emphysema, pulmonary fibrillin-1 expression is increased and positively correlated with distal airspace enlargement as well as the degree of parenchymal destruction, suggesting that elevated fibrillin-1 expression is associated with the early onset of lung emphysema." (PMID 40692090, 2025). "Due to the pathological structure of fibrillin 1, the development of emphysema can be often observed in these patients." (PMID 31089858, 2019). "Fbn1 is clearly important for alveolarization and the structural homeostasis of the alveoli, since Fbn1−/− mice exhibited an alveolarization defect, and fibrillin fibers were fragmented and disorganized in emphysema." (PMID 26779482, 2015). "Although we could not detect any signs of septal degradation in the CD-VAD group, we cannot exclude the possibility that pulmonary emphysema, possibly triggered by the high fibrillin-1 abundance, might have occurred at a later time point." (PMID 40692090, 2025). "Apparently, emphysema in TSK/+ mice is not owing to the mutated fbn-1 gene that is responsible for the occurrence of cutaneous hyperplasia, because transgenic mice bearing a mutated fbn-1 gene developed cutaneous hyperplasia but did not exhibit pulmonary emphysema." (PMID 17049072, 2006). "The mice lacking elastin or elastic fiber proteins, such as fibrillin-1, show an emphysema-like lung at birth." (PMID 24886716, 2014).
Hypertension (10 papers, 2011 to 2026). The presence of chronic increased pressure in the systemic arterial system. "Moreover, the FBN1 positive-variant group showed a tendency for a less frequent history of hypertension (45.5 vs. 58.2%) and smoking (9.1 vs. 27.8%)." (PMID 35154271, 2022). "Hypertension was found in FBN1 gene mutations encoding fibrillin and in PRKG1 mutations." (PMID 33807627, 2021). "Additionally, in two large population studies, the G–A substitution in FBN1 (rs11856553) was associated with moderate to severe prevalent hypertension." (PMID 33807627, 2021). "Hypertension was found in mutations of FBN1 gene encoding fibrillin, which may evolve with marfanoid habitus." (PMID 33807627, 2021). "Hypertension in a young patient with a TAA may point to a search of FBN-1, PRKG1 or other aorthopathy genes mutations." (PMID 33807627, 2021). "Fibrillin-1 is an extracellular matrix protein with load-bearing and anchoring functions in the arterial wall, directing the orientation of elastin fibers associated with aortic and arterial stiffness; FBN1 genotypes may thus contribute to hypertension." (PMID 33807627, 2021). "FBN1 may cause glomerular damage in hypertension and diabetic nephropathy." (PMID 38269088, 2023). "It is worth noting that in our study, patient #54 with three VUSs (in genes FBN1, COL3A1, and PLOD3) has only one CVD risk factor: arterial hypertension." (PMID 39125885, 2024). "Mice with hypertension induced by DOCA salt or diabetes induced by streptozotocin (STZ) exhibit a significant increase in glomerular FBN1 deposition." (PMID 38269088, 2023). "One hypertension SNP at time 2, rs11636344, in FBN1 gene and another SNP rs17722281 of WWOX gene from multivariate have been previously found to be associated with hypertension in China population." (PMID 24565370, 2013). "Intriguingly, a history of hypertension was significantly more prevalent in patients without FBN1 mutation." (PMID 26272055, 2015). "Herein, it is inferred that hypertension is not a primary element involving the primary pathogenesis of STAAD with FBN1 mutations." (PMID 26272055, 2015). "Moreover, the FBN1 positive-variant group show a lower frequency of history of hypertension and smoking than FBN1 negative-variant group, which are well-known risk factors for AD." (PMID 35154271, 2022). "On the contrary, in a large Chinese cohort, hypertension was more prevalent in patients without the FNB1 mutation (30.4% of patients with FBN1 mutations had hypertension versus 62.6% in the patients without the mutation), wherein the Ala27Thr substitution was more frequent." (PMID 33807627, 2021). "In addition, 30.4% of the patients with FBN1 mutation had a clinical history of hypertension vs. 62.6% of the patients without (P = 0.006)." (PMID 26272055, 2015). "Fibrillin-1 was also increased with CNT/F exposure, which has been reported to enhance arterial and myocardial thickening and hypertension." (PMID 34711247, 2021).